CLIC1 (CLIC family member 1)
Description:
In the soluble state, catalyzes glutaredoxin-like thiol disulfide exchange reactions with reduced glutathione as electron donor. Reduces selenite and dehydroascorbate and may act as an antioxidant during oxidative stress response. Can insert into membranes and form voltage-dependent multi-ion conductive channels. Membrane insertion seems to be redox-regulated and may occur only under oxidizing conditions. Involved in regulation of the cell cycle.
Synonyms: NCC27; G6; p64CLCP; CLCNL1; CL1C1
Tractability: Small molecule: a structure with a bound ligand is known; it has a binding pocket of medium quality. Antibody: UniProt places it where antibodies can reach, with high confidence; UniProt predicts a signal peptide or a membrane-spanning region; its Gene Ontology location is reachable by antibodies, with medium confidence. PROTAC: ubiquitination databases record sites on it; its protein half-life has been measured.
Target class: Enzyme; Oxidoreductase
Gene: Protein-coding gene on chromosome 6 (31,730,581 to 31,740,558, reverse strand). Ensembl gene ENSG00000213719.
Subcellular location: Nucleus; Nucleus membrane; Cytoplasm; Cell membrane; Endoplasmic reticulum
Subcellular location (Human Protein Atlas): Cytosol
Gene Ontology:
Molecular function: cadherin binding; chloride channel activity; glutathione dehydrogenase (ascorbate) activity; protein binding
Biological process: chloride transport; platelet aggregation; signal transduction; cellular oxidant detoxification; chloride transmembrane transport
Cellular component: blood microparticle; cytoplasm; cytosol; extracellular exosome; extracellular region; membrane; nuclear envelope; nuclear membrane; nucleus; perinuclear region of cytoplasm; plasma membrane; vesicle; brush border; endoplasmic reticulum; mitochondrion
Genetic constraint (gnomAD): Loss-of-function variants: 16 observed, 27.42 expected, observed/expected ratio (o/e) 0.58, 90% interval 0.39 to 0.89. The upper end of that interval is the gene's LOEUF score, 0.89, which puts it in group 3 of 6, group 1 being the genes least tolerant of losing a copy. Missense variants: 225 observed, 294.41 expected, observed/expected ratio (o/e) 0.76, 90% interval 0.69 to 0.85. Synonymous variants: 98 observed, 123.52 expected, observed/expected ratio (o/e) 0.79, 90% interval 0.67 to 0.94.
Homologues: Orthologues: chimpanzee CLIC1 (100% identical), macaque CLIC1 (99% identical), dog CLIC1 (98% identical), mouse Clic1 (98% identical), rabbit CLIC1 (98% identical), guinea pig CLIC1 (96% identical), rat Clic1 (94% identical), zebrafish clic1 (76% identical), tropical clawed frog clic1 (72% identical), Caenorhabditis elegans exc-4 (28% identical), Caenorhabditis elegans exl-1 (27% identical), Drosophila melanogaster Clic (24% identical), and 28 more. Paralogues in human: CLIC4 (67% identical), CLIC6 (65% identical), CLIC5 (63% identical), CLIC2 (60% identical), CLIC3 (51% identical), EEF1G (22% identical), GSTT2 (22% identical), GSTT2B (22% identical), GDAP1 (20% identical), GSTT4 (19% identical), GDAP1L1 (17% identical), GSTO2 (17% identical), and 2 more.
Diseases named in the same sentence as CLIC1 in open-access papers:
CLIC1 is named in the same sentence as 104 diseases in open-access papers, as found by Europe PMC text mining. Sharing a sentence is not in itself a finding about the gene and the disease. The quoted sentences say what the papers report.
glioblastoma (34 papers, 2014 to 2025). The most malignant astrocytic tumor (WHO grade IV). "Various patient-derived glioblastoma cells with different genetic backgrounds were used to demonstrate that CLIC1 CRISPR-Cas9 knockout and/or its point mutation at arginine 29 removes metformin’s antitumor effects." (PMID 41276810, 2025). "The membrane integration of CLIC1 accompanied by a higher tumor aggressiveness was underlined by Setti in glioblastoma cases, as well as Peretti." (PMID 36826036, 2023). "We have discovered the activation of CLIC1 Cl− efflux by intracellular Zn2+ in glioblastoma cells, which also causes CLIC1 relocalisation to the plasma membrane." (PMID 35833483, 2022). "In glioblastoma, the CLIC1 channel protein is overexpressed and correlates with lower survival rates." (PMID 40535121, 2025). "Accordingly, a novel class of biguanide-based derivatives used as CLIC1-inhibitors has been recently developed and holds promises for the treatment of CLIC1-expressing glioblastomas." (PMID 38188666, 2023). "Endogenous CLIC1 localisation was monitored in HeLa and glioblastoma cells (U87G) using immunostaining." (PMID 35833483, 2022). "Metformin exerts antitumor effects in glioblastoma stem cells (GSCs) inhibiting CLIC1 activity, but its low potency hampers its translation in clinical settings." (PMID 35135603, 2022). "In the same study, the injection of glioblastoma cells with EVs containing CLIC1 into nude mice enhanced tumor growth when compared with EVs not containing CLIC1." (PMID 32384712, 2020). "Surprisingly, extracellular vesicles were reported to transfer CLIC1 from glioblastoma cells to microvascular epithelial cells, perhaps contributing to metastasis in targeting cells." (PMID 32116799, 2020). "In glioblastoma, CLIC1-mediated channel activity was recorded to distinguish cytosolic vs membranous components." (PMID 32116799, 2020). "This indicated treatment with CLIC1 antibodies produces an obvious decrease in in vivo tumorigenicity of glioblastoma cells." (PMID 28264681, 2017). "Silencing of chloride intracellular channel 1 (CLIC1), which is significantly overexpressed in stem/progenitor cells from human glioblastomas, reduced the proliferative and clonogenic capacity of stem/progenitor cells." (PMID 28219421, 2017). "Meanwhile, glioblastoma cells exposed toisotype control antibodies or CLIC1 antibodies were transplanted into the brains of immunodeficient mice." (PMID 28264681, 2017). "Within the Cl- intracellular channels, CLIC1 expression was found altered in bladder cancer and glioblastoma." (PMID 27716384, 2016). "CLIC1 was found to be enriched and promote proliferation, colongenic and tumorigenic capacity in the glioblastomas stem cell." (PMID 27825122, 2016). "CLIC1 has been previously found up-regulated in glioblastoma, it is involved in different tumors and acts as an oncogene in pancreatic cancer, and has been indicated as a possible cancer biomarker." (PMID 27716384, 2016). "Here we show that chloride intracellular channel-1 (CLIC1) is a direct target of metformin in human glioblastoma cells." (PMID 25361004, 2014). "Additionally, CLIC1 expression in glioblastoma stem cells (GSCs) correlates with poor prognosis, and its inhibition via RNA silencing or antibody targeting reduces proliferation, clonogenicity, and tumorigenicity both in vitro and in vivo." (PMID 40806720, 2025). "Moreover, TRPM7 in glioblastoma cells has been reported to promote the vesicular transfer of chloride intracellular channel 1 (CLIC1) from glioblastoma to endothelial cells." (PMID 38255793, 2024). "Besides, chloride intracellular channel-1 (CLIC1) was reported to boost proliferation, and its functional expression is required for metformin antineoplastic effects in glioblastomas and gallbladder cancer cells." (PMID 37344841, 2023).
glioblastoma (continued). "Interestingly, CLIC1 inhibitors has also been explored in glioblastoma cells and found that inhibition of CLIC1 sensitizes glioblastoma stem cells by inhibiting proliferation, migration, invasiveness and self-renewable in vitro and in vivo." (PMID 36845715, 2023). "Chloride intracellular channel-1 (CLIC1) activity controls glioblastoma proliferation." (PMID 35135603, 2022). "In particular, the biguanide-based derivatives Q48 and Q54, represent the leads to develop novel compounds endowed with better pharmacological profiles than metformin, to act as CLIC1-blockers for the treatment of CLIC1-expressing glioblastomas, in a precision medicine approach." (PMID 35135603, 2022). "Several pre-clinical models reported the efficacy of metformin against glioblastoma cells, with different molecular mechanisms involving for example the chloride intracellular channel protein 1 (CLIC1), the AMP-activated protein kinase (AMPK), Akt and FOXO3 activation." (PMID 35326565, 2022). "Similar to gastric cancer cells, CLIC1 is shown to regulate ROS accumulation and pH changes in human glioblastoma stem cells influencing their proliferation as well as their motility, and therefore could be a crucial therapeutic target." (PMID 32116799, 2020). "Glioblastoma is an aggressive and common tumor type where CLIC1 is highly expressed." (PMID 32116799, 2020). "The currents correlate with the tumor aggressiveness indicating a positive correlation between membrane form of CLIC1 to glioblastoma, and these results indicate that CLIC1 could be translocated to the membranes in tumor environments." (PMID 32116799, 2020). "CLIC1 is the first member of the Chloride Intracellular Channel family; its expression has been correlated with poor prognosis and it is known to modulate the cell cycle progression of glioblastoma stem cells." (PMID 31803233, 2019). "Although several cell-specific intracellular mechanisms contribute to the anti-tumor activity of metformin, the inhibition of the chloride intracellular channel 1 activity (CLIC1) at G1/S transition is a key events in metformin antiproliferative effect in glioblastoma stem cells (GSCs)." (PMID 30186163, 2018). "In addition, the chloride intracellular channel 1 (CLIC1) is involved in development of the most aggressive human tumors, including glioblastoma." (PMID 28445150, 2017). "Previous studies suggested CLIC1 appears to have a broad tissue distribution; it has been most intensely studied in various tumor tissues like gastric cancer, colon cancer, lung cancer, liver cancers, and glioblastoma." (PMID 29147652, 2017). "Similarly, the chloride intracellular channel 1 (CLIC1) is overexpressed in glioblastoma, with the highest expression in patients with worse prognosis." (PMID 29261132, 2017). "In addition, a decrease in CLIC1-mediated Cl− currents and glioblastoma cell proliferation were also seen with CLIC1 antibody addition." (PMID 28264681, 2017). "CLIC1 was found to be transferred by extracellular vesicle and regulation the glioblastoma growth." (PMID 27825122, 2016). "We identified CLIC1 not only as a modulator of cell cycle progression in human glioblastoma stem cells but also as the main target of metformin's antiproliferative activity, paving the way for novel and needed pharmacological approaches to glioblastoma treatment." (PMID 25361004, 2014). "Metformin inhibition of CLIC1 activity induces G1 arrest of glioblastoma stem cells." (PMID 25361004, 2014). "Similarly, EVs from glioblastoma cells transfer CLIC1 protein to support tumor growth." (PMID 39132504, 2024). "CLIC1 is overexpressed in glioblastoma (GBM), with highest expression in patients with poor prognosis." (PMID 30279961, 2018). "For example, CLIC1 is involved in the development of most aggressive human tumors, including glioblastoma (GBM) and lung adenocarcinoma." (PMID 29147652, 2017).
glioblastoma (continued). "CLICs, mainly CLIC1 and CLIC4, are significantly overexpressed in several malignancies, including glioblastoma, prostate, colon, and HCC." (PMID 40806720, 2025). "New biguanide compounds Q48 and Q54 block CLIC1 more effectively than metformin, reducing GSC proliferation, invasion, and self-renewal with minimal toxicity, showing promise as targeted glioblastoma therapies." (PMID 40806720, 2025). "Chloride intracellular channel 1 (CLIC1) is highly expressed and secreted by human glioblastoma cells and cell lines such as U87, initiating cell migration and tumor growth." (PMID 30279961, 2018). "Within the shadowed columns, glioblastoma appears to have the highest number of modified ion-channel genes (namely: FXYD5, KCNE3, KCNE4, CLIC1, TRPM3)." (PMID 27716384, 2016). "In glioblastoma, which is driven by CSCs, CLIC1 has been shown to be selectively active in CSCs but not in mesenchymal stem cells (MSCs) and is crucial for their proliferation and self-renewal." (PMID 40806720, 2025). "Few studies have suggested that CLIC1-positive tumor cells communicate with endothelial cells by releasing CLIC1 extracellular vesicles with affinity for different endothelial cell receptors, such as TRMP7, for glioblastoma cells or colocalize with CLT1 on angiogenic tumor blood vessels." (PMID 36497464, 2022). "Another study demonstrated that EVs released by glioblastoma cells (either cell lines or patient-derived cancer stem cells) mediated the intercellular transfer of the protein chloride intracellular channel-1 (CLIC1), supporting the growth of other (recipient) glioblastoma cells." (PMID 32384712, 2020).
gastric cancer (24 papers, 2009 to 2025). A primary or metastatic malignant neoplasm involving the stomach. "Increasing evidence indicates that CLIC1 is associated with a variety of malignancies, including pleomorphic human sarcoma, glioblastoma, ovarian cancer, liver cancer, pancreatic cancer, gastric cancer and colorectal cancer." (PMID 33856653, 2021). "Chloride intracellular channel 1 (CLIC1) is an ion channel that is significantly related to drug resistance in gastric cancer cells." (PMID 39135913, 2024). "Other studies have found that highly expressed CLIC1 can effectively inhibit the proliferation of gastric cancer cells in vitro and enhance the apoptosis, migration, and invasion of gastric cancer cells." (PMID 39346794, 2024). "A linkage to MAPK signaling has already been reported for one of these genes, chloride intracellular channel 1 (CLIC1), in the context of gastric cancer progression." (PMID 39835134, 2024). "In gastric cancer, the involvement of CLIC1 in metastatic progression was observed by reducing AMOT-p130 expression." (PMID 36826036, 2023). "Several studies have demonstrated the expression of CLIC1 either in gastric cancer tissues or colon cancer cells; therefore, it is likely to be beneficial in clinical practice as a potential tumor marker." (PMID 36826036, 2023). "In gastric cancer, CLIC1 absence impedes invasion and migration by affecting AMOT-p130 expression, possibly contributing to metastasis." (PMID 38053842, 2023). "High CLIC1 levels have been found in a variety of malignant tumors, including cervical cancer, breast cancer, hepatocellular carcinoma, gastric cancer, gallbladder carcinoma, and CRC." (PMID 36797245, 2023). "Surprisingly, gastric cancer patients with higher expression of CLIC1 have a higher rate of survival." (PMID 32116799, 2020). "Elevation of chloride intracellular channel 1 (CLIC1) is strongly correlated with lymph node metastasis, lymphatic invasion and pathological staging in gastric cancer." (PMID 32066374, 2020). "Earlier studies by our group have shown that SPARC, CLIC1, SLPI, CXCL1, CXCL8, and CXCR2 are highly expressed and associated with advanced stages and poor prognosis of gastric cancer." (PMID 22479608, 2012). "Research focusing on gastric cancer has indicated that CLIC1 might control the expression of ITG family proteins, resulting in the consecutive activation of PI3K/AKT, MAPK/ERK, and MAPK/p38 pathways." (PMID 40948771, 2025). "Moreover, the study indicated that CLIC1 regulates gastric cancer cell migration and invasion via the ROS-mediated p38 MAPK signaling pathway." (PMID 38956367, 2024). "Furthermore, CLIC1 is associated with proteasome activator 28 β (PA28 β), and its specific siRNA downregulates CLIC1 in gastric cancer." (PMID 35205604, 2022). "CLIC1 is overexpressed in several cancers including liver cancer, gall bladder cancer, pancreatic ductal adenocarcinoma, glioma, breast cancer, nasopharyngeal carcinoma, and gastric cancer to name a few." (PMID 32116799, 2020). "Furthermore, functional inhibition of CLIC1 downregulates ROS production in gastric cancer cells and decreases gastric cancer cell migration and invasion." (PMID 32116799, 2020). "Similarly, proteomics profiling of tumor tissues from gastric cancer revealed CLIC1 to be significantly up-regulated in 67.9% of the patients." (PMID 21342498, 2011). "This study revealed significant correlation between elevated expression of CLIC1 and lymph node metastasis, lymphatic invasion, perineural invasion, advanced pathological stage and poor survival in gastric cancer, which highlights the role of CLIC1 in tumor invasion and metastasis in gastric cancer." (PMID 21342498, 2011). "In gastric cancer, the absence of CLIC1 impedes invasion and migration, likely by increasing the expression of AMOT-p130." (PMID 38027011, 2023).
gastric cancer (continued). "In summary, CLIC1 plays a crucial role in various cancers, including breast cancer, ESCC, lung adenocarcinoma, gastric cancer, and HCC, making it a potential target for cancer treatment due to its influence on cell proliferation, migration, invasion, and metastasis." (PMID 38053842, 2023). "CLIC1 also modulates MAP kinase and AKT signaling to promote gastric cancer, which could implicate CLIC1 in modulating signaling pathways through ROS." (PMID 32116799, 2020).